DDX3X (DEAD-box helicase 3 X-linked)
Diseases named in the same sentence as DDX3X in open-access papers (continued):
Sharing a sentence is not in itself a finding about the gene and the disease.
tumor (139 papers, 2011 to 2026). "Chi-square (and Fisher’s exact) test demonstrated an association between DDX3X expression and elevated serum alpha-fetoprotein levels, larger tumor size as well as advanced TNM stage." (PMID 41198618, 2025). "Focusing on the more numerous DDX3X mutations, among virus-positive tumor samples they were detected in 49% (67/136) BL, 29% (4/14) ANKL, 19% (19/100) NKTCL, 1.2% (1/86) cHL, 5% (4/81) ATL, 3% (1/30) PBL, 3% (2/60) HNSCC, and 2% (3/144) of CC." (PMID 40595559, 2025). "As anticipated from the critical roles of DDX3X, mutations in DDX3X are linked to pathogenic processes such as tumor progression in medulloblastoma." (PMID 38664397, 2024). "Next, we analyzed a large RNA seq dataset (SEQC‐498) from 498 NB tumors to examine the association of DDX3X with tumor aggression." (PMID 37975412, 2024). "We demonstrate the utility of these data for clinical variant classification in NDDs, and demonstrate that DDX3X predominantly acts as a tumour suppressor gene across multiple tumour types." (PMID 38057330, 2023). "DDX3X functions as a tumor-suppressor gene in MB; its functional deletion mutation increased the incidence and severity of tumor formation in mouse models of WNT and SHH MBs." (PMID 36937322, 2023). "DDX3X regulates hindbrain patterning, and its loss removes lineage restriction toward tumor formation, allowing for the onset of WNT MB from either lower or upper rhombic lips." (PMID 35706426, 2022). "For instance, increased tumor malignancy and poor treatment outcome in non-small-cell lung carcinoma were associated with loss of DDX3X." (PMID 34680866, 2021). "We next sought to dissect the molecular mechanism of low DDX3X-associated tumor progression that leads to poor outcomes in RCC patients." (PMID 32326089, 2020). "In a gene gravity model, tumor genomes harboring DDX3X nonsynonymous somatic mutations appear to have high mutation density." (PMID 31906196, 2019). "Subgroups 1 and 2 are associated with aberrant Wnt/β-catenin and sonic hedgehog (SHH) signaling, respectively, and all identified DDX3X mutations belonged to tumor samples of the Wnt or SHH subgroups." (PMID 29222110, 2018). "The DEAD (Asp-Glu-Ala-Asp) box helicase 3, X-linked (DDX3X) controls tumor migration, proliferation, and progression." (PMID 26184164, 2015). "Conversely, tumor cells may hijack these mechanisms to ectopically express DDX3Y to overcome the loss of DDX3X." (PMID 39975375, 2025). "The physiological importance of the translational regulation dictated by DDX3X is supported by findings that the mutations causing DDX3X dysfunction are frequently linked to pathological processes such as tumor progression, developmental disorders, and intellectual disability." (PMID 40877262, 2025). "Moreover, studies have revealed the role of DDX3X in tumorigenesis and tumor progression, but the precise function and underlying mechanisms are controversial." (PMID 37988165, 2023).
tumor (continued). "While it is possible that DDX3X missense mutations contribute to tumorigenesis through inhibited expression of a specific tumor suppressor, an alternative possibility is that altered translation due to DDX3X mutations contributes to tumor development as an adaptive mechanism to metabolic stress." (PMID 27180681, 2016). "Furthermore, NGS testing identified mutations in the JAK2 and DDX3X genes in this patient, indicating that the disease is heterogeneous at the genetic level and may contribute to the malignant transformation of tumor cells." (PMID 40666527, 2025). "A tumor suppressor role has been recently hypothesized for DDX3X, often found mutated in WNT MB." (PMID 35706426, 2022). "In the CRISPR screen, DDX3X showed a greater dependency in female-derived cell lines, providing additional evidence of a sex-dependent functional effect in tumours." (PMID 39975298, 2025). "This dual nature aligns with prior findings, where DDX3X can function both as an oncogene and a tumor suppressor depending on the cellular and molecular context." (PMID 40564907, 2025). "A small molecule DDX3X inhibitor, RK-33, has demonstrated significant potential in promoting tumor regression and enhancing sensitivity to radiotherapy." (PMID 40885716, 2025). "Collectively, these in vivo findings underscored DDX3X’s oncogenic role in promoting HCC tumor growth and metastasis." (PMID 41198618, 2025). "Next, we purified primary lung tumor cells and conducted tumor spheroid assays, which indicated that ablation of DDX3X significantly impaired tumor spheroid formation." (PMID 40885716, 2025). "DDX3X has been demonstrated to be highly expressed in numerous malignancies and contributes to oncogenic processes in tumor progression." (PMID 41198618, 2025). "The X-linked gene DDX3X, homolog of Y-linked DDX3Y, has been implicated as a sex-differing tumor suppressor by higher loss of function mutation rates in male compared to female cancers." (PMID 39975298, 2025). "In a subcutaneous tumor model, we observed that the knockdown of DDX3X in MHCC97-H cells resulted in a significant reduction in both tumor volume and weight." (PMID 41198618, 2025). "Our next objective was to compare the anti-tumor efficacy of J10 with RK-33, a small molecule DDX3X inhibitor that has been shown to have anti-tumor effects." (PMID 40885716, 2025). "Previous studies have revealed a link of DDX3X to both oncogenic and tumor-suppressive pathways, making it an interesting candidate for functional validation and therapeutic investigation." (PMID 40564907, 2025). "IHC results indicated that the average expression level of DDX3X was elevated in HCC tissues relative to adjacent non-tumor tissues." (PMID 41198618, 2025). "RK-33 is a small molecule that binds to the ATPase domain of DDX3X, thereby inhibiting its helicase unwinding activity, which is crucial in tumor biology." (PMID 41198618, 2025). "The results verified that DDX3X expression is notably upregulated in the tumor tissue vs. normal tissue of PDAC patients." (PMID 38316768, 2024). "Particularly, immunotherapies targeting neoantigens from oncogenic driver mutations such as CTNNB1, DDX3X, and SMARCA4 and TAAs which have possible implications in tumor progression such as NEUROG1 and PIK3R3 are attractive for a better outcome in patients." (PMID 39160595, 2024). "The upregulation of DDX3X at the protein level in tumor tissues was also validated through immunohistochemistry (IHC) staining and H&E staining of human PDAC samples." (PMID 38316768, 2024). "Loss of DDX3X would thus reduce cell death and promote WNT- and/or SHH-dependent oncogenesis in these lineages, suggesting that DDX3X is a tumor suppressor." (PMID 39062517, 2024). "DDX3X expression on WNT and SHH has priorly been known and is implicated in the survival, growth, and malignant potential of the tumor cells." (PMID 39160595, 2024).
tumor (continued). "The therapeutic potential of targeting DDX3X was highlighted in mouse studies in which depletion of DDX3X reduced tumor growth and promoted anti-tumor immunity." (PMID 39221819, 2024). "In this issue of the JCI, Wenrui Zhang and colleagues show that within a hostile tumor microenvironment asparagine endopeptidase (AEP) triggers an AS-biogenesis cascade in solid tumors by cleaving the RNA helicase DDX3X." (PMID 38299588, 2024). "Loss of Kindlin-2 blocked DDX3X from binding to the 5'-untranslated region of c-Myc and inhibited DDX3X-mediated c-Myc translation, leading to reduced c-Myc-mediated glucose metabolism and tumor growth." (PMID 37649609, 2023). "Together, these data support the argument that DDX3X predominantly acts as a tumour suppressor gene across multiple tumour types." (PMID 38057330, 2023). "Western blot results demonstrated that mature AEP and cleaved DDX3X were found mainly in tumor compared to adjacent normal tissue." (PMID 37988165, 2023). "In spite of these studies indicated that DDX3X is an important regulator of tumor cell apoptosis, the functional role of DDX3X in endothelial injury was unclear." (PMID 37149668, 2023). "The tumor-promoting effect of DDX3X was partially attributed to its ability to regulate the expression of multiple cell cycle-associated genes and thus promote the G1/S transition." (PMID 37845393, 2023). "Inhibiting ATP-dependent RNA helicase DDX3X’s ATP binding domain with the small molecule RK-33 was one of choices, and the effect was discovered to synergize with radiotherapy to reduce tumor cells’ proliferation in vitro and in vivo." (PMID 37371098, 2023). "In conclusion, our study reveals the interaction between AEP and DDX3X, which provides a new layer of knowledge regarding protease-mediated regulation of AS in the harsh tumor microenvironment." (PMID 37988165, 2023). "DDX3X KD significantly inhibited the proliferative capacity of tumor cells, while rescue with WT DDX3X effectively alleviated this impairment in proliferation." (PMID 37988165, 2023). "DDX3X, the DEAD (Asp-Glu-Ala-Asp) box helicase 3, X-linked, is involved in various aspects of tumor migration and proliferation." (PMID 35409289, 2022). "The role of DDX3X in malignancy remains controversial, and it has been classified as both a tumor suppressor and an oncogene." (PMID 36497332, 2022). "In this carcinoma, DDX3X facilitates tumor metastasis enhancing the expression of the oncogene KRAS by promoting SP1 transcription factor binding to the KRAS promoter." (PMID 35954483, 2022). "DDX3X-depleted breast tumor also exhibited tumor-intrinsic innate immune activation and increased tumor-infiltrated cytotoxic T cells and DCs in a syngeneic mouse model." (PMID 35874614, 2022). "In fact, knockdown of DDX3X upregulates cyclin D1 and downregulates p21, thus promoting cell cycle progression to the S phase and facilitating tumor cell growth." (PMID 35954483, 2022). "DDX3X can indeed act as an oncogene and/or a tumor suppressor by altering different molecular pathways that either enhance or block tumor cell proliferation." (PMID 35954483, 2022). "By facilitating the translation of Rac1 mRNAs containing a structured 5′UTR, DDX3X stabilizes β-catenin, thus increasing the expression of its downstream transcriptional targets involved in tumour metastasis, including MMP14, Pld1 and Stat3." (PMID 33627125, 2021). "Over two decades, many studies have gradually unveiled the role of DDX3X in tumorigenesis and tumour progression." (PMID 33627125, 2021). "Among the inhibitors of the DDX3X ATPase activity, compound RK-33 was able to reduce tumor volume in xenograft Ewing Sarcoma and in preclinical lung and prostate cancer models in association with radiotherapy." (PMID 34771731, 2021). "Most studies have indicated high cytoplasmic DDX3X expression in tumour tissues, and some of them indicate that this predicts poor prognosis." (PMID 33627125, 2021).
tumor (continued). "Tumor masses were also analyzed for the expression of DDX3X, and all xenografts resulted positive for DDX3X expression, from both control and treated groups, with a spotted staining pattern." (PMID 34771731, 2021). "Some, such as FGF13 and DDX3X, have earlier been shown to have a role in tumor behavior, though their dimorphic effects in males and females have not been identified." (PMID 34621669, 2021). "One study has shown that six of such genes show increased loss-of-function mutations in male tumor diseases (ATRX, CNKSR2, DDX3X, KDM5C, KDM6A, and MAGEC3)." (PMID 32629877, 2020). "Our quantification of the DDX3X protein concentrations in several tumor cell lines, revealed that many of them have levels of DDX3X close to the concentrations used in our in vitro systems." (PMID 33137198, 2020). "Targeting DDX3X through blocking its ATP binding domain with the small molecule RK-33 synergizes with radiotherapy to decrease tumor cells proliferation in vitro and in xenograft models in vivo." (PMID 31906196, 2019). "The exact function of DDX3X is affected by its interacting partners and is tumor and/or context dependent." (PMID 31906196, 2019). "Many reports have focused on DDX3X and their association with cancers, and the mutation has a possibility of a common driver mutation of EBV-positive neoplasms." (PMID 30805320, 2019). "Statistical analysis of GEO datasets showed that DDX3X mRNA expression demonstrated statistically higher in WHO grade IV (n = 81) than in non-tumor controls (n = 23, p = 1.13 × 10−10)." (PMID 26184164, 2015). "The DDX3X expression level was higher in WHO grade IV (n = 81) than in non-tumor controls (n = 23) (p = 1.13 × 10−10)." (PMID 26184164, 2015). "Although DDX3X was originally reported to suppress tumor growth by modulating p21waf/cip1 gene expression, DDX3X has also been shown to be directly correlated with oncogenesis." (PMID 25343452, 2014). "Notably, arginine restriction or pharmacological inhibition of DDX3X did effectively suppress both primary tumor growth and omental metastasis in mouse models." (PMID 41876452, 2026). "The log2 transformed fold change of DDX3X in HCC revealed that overexpression of DDX3X defined as a >1-fold increase-was observed in 18 out of 20 (90%) pairs of primary HCC tumors compared to adjacent non-tumor tissues." (PMID 41198618, 2025). "Additionally, we assessed DDX3X expression in a tissue microarray comprising 122 pairs of HCC and adjacent non-tumor tissue samples with associated clinicopathological features." (PMID 41198618, 2025). "Additionally, DDX3X deficiency triggers aberrant activation of NF‐κB and MAPK pathways, dysregulating cell cycle control and promoting tumour aggressiveness." (PMID 39823244, 2025). "The results also show that RK-33 slowed down tumor progression across all three BL models, but that Pevonedistat proved more effective which suggests the cell lines developed alternative survival mechanisms against DDX3X inhibition in vivo." (PMID 40772229, 2025). "Moreover, we unveiled co‐occurrence relationships among ITSGs in tumour mutations, such as TIPARP with DDX3X and HERPUD1 with DNAJB1." (PMID 39031800, 2024). "Considering that DDX3X has been shown to promote tumor proliferation in nude mice, we further investigated whether there was any relationship between the expression patterns of DDX3X and the proliferation marker Ki67 in PDAC patients." (PMID 38316768, 2024). "Depending on the specific tumor type, DDX3X may function as either an oncogene or a tumor suppressor." (PMID 38316768, 2024). "Furthermore, SIRT7 inhibition significantly impeded DDX3X-mediated tumor growth both ex vivo and in vivo." (PMID 38316768, 2024).
tumor (continued). "Furthermore, Western blotting (WB) and IHC were performed on KPC mice compared to WT mice, which confirmed that DDX3X was significantly upregulated in the tumor tissues." (PMID 38316768, 2024). "Taken together, our data indicate that DDX3X promotes tumor growth in vivo." (PMID 38316768, 2024). "The full-length DDX3X is located in both the cytoplasm and nucleus of tumor cells." (PMID 38299588, 2024). "Ddx3X demonstrates functional diversity across different tumor types and diseases." (PMID 38993792, 2024). "Acting as an adapter that bridges the E3-ligase CUL3 and the substrate DDX3X, KLHL29 executes the tumor suppressive function by enhancing the proteasomal degradation of DDX3X, consequently leading to the downregulation of cyclins and cell cycle arrest at G0/G1 phase." (PMID 37845393, 2023). "DDX3X is an RNA helicase gene that is one of the most commonly mutated genes in ENKTL, with significant upregulation of the NF-κB and MAPK pathways found in DDX3X-mutated ENKTL tumors, suggesting that DDX3X is a possible tumor suppressor." (PMID 36900160, 2023). "Most papers indicated that DDX3X acted as a tumor promoter in CRC." (PMID 38023215, 2023). "The prognostic role of DDX3X is a critical factor in determining whether DDX3X plays an oncogenic or tumor-suppressive role." (PMID 37371098, 2023). "In addition, DDX3X promotes KRAS-dependent tumor invasion by activating the β-catenin/ZEB1 pathway that requires β-catenin/TCF4 activation by DDX3X through the Wnt/CK1ε/Dvl2 axis." (PMID 35954483, 2022). "HIF-1α, in turn, increases DDX3X expression, thus further promoting tumor progression." (PMID 35954483, 2022). "The subcellular localization of DDX3X seems to determine the fate of the tumour as well." (PMID 33627125, 2021). "Mechanistically, DDX3X represses the expression of stemness genes via upregulation of the expression of a subset of tumour-suppressive miRNAs, including miR-200b, miR-200c, miR-122 and miR-145, by reducing DNMT3A (DNA methyltransferase 3A) binding and hypermethylation on their promoter regions." (PMID 33627125, 2021). "Although the functions of DDX3X have been gradually revealed, controversy persists as to whether regarding its identity as a tumour suppressor or oncogene has been ongoing." (PMID 33627125, 2021). "Collectively, an inability of the death receptors to disable DDX3X activity may contribute to resistance to death receptor-induced apoptosis in tumours, suggesting that targeting DDX3X might be a useful strategy for promoting death receptor-induced apoptosis." (PMID 33627125, 2021). "Furthermore, low DDX3X was also correlated with late disease stage, large tumor size and distant metastasis." (PMID 32326089, 2020).